FTO (FTO alpha-ketoglutarate dependent dioxygenase)
Diseases named in the same sentence as FTO in open-access papers (continued):
Sharing a sentence is not in itself a finding about the gene and the disease.
Obesity (continued). "Based on the surveyed population, a 1:1 pair-matched case-control study was designed to determine the association between FTO (rs1121980 and rs17817449) and MC4R gene (rs17782313 and rs12970134) polymorphisms with obesity in Tibetan adults." (PMID 38279121, 2024). "DNA methylation is closely related to the development of obesity by affecting gene expression, then disrupting the regulatory balance between obesity-promoting genes (such as FTO and PPARγ) and anti-obesity genes (such as LEP, GLP-1R, and POMC)." (PMID 39200098, 2024). "The variants of the FTO SNPs are present in 47 kb linkage disequilibrium blocks covering the portion of 1st two introns and exon 2 of the FTO gene that is related to obesity and high body mass index." (PMID 39253342, 2024). "The link between SNPs in the FTO gene and obesity has been uncovered through GWAS as mentioned in the previous chapter." (PMID 39744011, 2024). "FTO has been identified as a significant factor in a broad spectrum of human health issues, including obesity, diabetes mellitus, cardiovascular disorders, neurological anomalies, and various oncological conditions." (PMID 39175477, 2024). "Given that WC and WHR are useful predictors of abdominal obesity, this study highlights the potential role of the CLOCK, FTO, and LEP gene variants in increasing the risk of this type of obesity, which is often associated with cardiovascular disease." (PMID 39203789, 2024). "In humans, FTO regulates adipogenesis through tyrosine protein kinase, Cyclin-A2, and cyclin-dependent kinase 2, demonstrating an interaction between FTO and obesity at multiple levels of human metabolism." (PMID 38902235, 2024). "Studies on different ethnicities have demonstrated that genetic variations in FTO gene influence the development of obesity." (PMID 38973101, 2024). "Following the initial discovery of FTO’s implication in human obesity, this gene has garnered significant attention in other metabolic diseases such as T2D, non-alcohol fatty liver disease (NAFLD), hypertension, cardiovascular diseases, and OP." (PMID 39336743, 2024). "Specifically, CLOCK/CC, FTO/AA, and LEP/AA genotypes were strongly associated with higher obesity metrics and emotional eating scores, while GHRL/TT and MC4R/CC were linked to increased BMI and WHR." (PMID 39203789, 2024). "According to multiple studies, the FTO gene is one of the genes determining the complex genetic basis of obesity and its consequences metabolic consequences." (PMID 39671348, 2024). "Obesity research suggests that the FTO gene region alters the function of nearby genes (IRX3 and IRX5), which impact the involvement of fat cells in thermogenesis." (PMID 38746260, 2024). "Another study noticed the synergistic impact of other genes such as peroxisome proliferator-activated receptor gamma (PPARγ), FTO, and melanocortin-4 receptor (MC4R)—in the predisposition to overweight and obesity." (PMID 38397196, 2024). "Overexpression of FTO in mice leads to increased food intake and obesity, whereas fto mice display reduced growth and lower body mass." (PMID 39669404, 2024). "In the present study, it was found that the FTO rs9939609 variant and physical inactivity are the main variables related to an increased risk for class III obesity." (PMID 38610209, 2024). "The objective of this study was to shed light on the potential involvement of the FTO gene in postmenopausal OP by analyzing five common SNVs in intron 1, known from previous studies for their implications in human obesity and/or insulin resistance." (PMID 39336743, 2024). "Though the FTO gene is mainly identified with obesity and the regulation of metabolism, pregnancy outcomes can be influenced indirectly." (PMID 39758312, 2024). "More randomised controlled intervention trials in adolescents with overweight and obesity are thus needed to investigate the role of the FTO genotype in the success of obesity interventions." (PMID 38556726, 2024).
Obesity (continued). "FTO was first discovered as a gene involved in obesity and energy metabolism and later introduced as the RNA m6A demethylase." (PMID 39136000, 2024). "Subsequent studies revealed that mice with multiple copies of the FTO gene became obese, while deleting this gene prevented obesity." (PMID 39192357, 2024). "The potential shared genetic background between obesity and psoriasis remains elusive, with limited studies exploring the role of the FTO gene in the pathogenesis of obesity among psoriatic patients, including the Polish psoriasis population." (PMID 38540130, 2024). "Early genome-wide related studies have demonstrated the impact of FTO on human obesity and homeostasis." (PMID 39296713, 2024). "As an obesity‐related protein, inhibition of FTO by entacapone can reduce the weight and fasting blood glucose concentration of mice." (PMID 38943267, 2024). "The FTO gene was evaluated by GWAS analysis (genome-wide association studies) and shown to be positively correlated with obesity; the studies were confirmed on murine models, where the FTO gene was overexpressed in obese-like models compared to the controls." (PMID 39057082, 2024). "Previous studies corroborate the effectiveness of quercetin and naringenin in binding to the FTO protein, contributing to anti-obesity effects." (PMID 39494311, 2024). "We aim to evaluate the relationship between FTO gene and overweight/obesity and confirm the influence of obesity on glucose and lipid metabolism parameters." (PMID 39483856, 2024). "Overexpression of FTO in mice led to increased food consumption and obesity whereas inactivation of FTO resulted in significant weight loss and growth retardation." (PMID 39296713, 2024). "Among all genes associated with fat mass and obesity, the FTO gene (FTO alpha-ketoglutarate-dependent dioxygenase) stands out with the strongest correlation." (PMID 38724937, 2024). "FTO is a major genetic link between breast cancer, obesity, and diabetes PPARG regulates adipocyte differentiation, lipid storage, and glucose metabolism, affecting insulin sensitivity and linking it to obesity, metabolic syndrome, and type 2 diabetes." (PMID 39769194, 2024). "Studies suggested that the abnormal N6-methyladenosine (m6A) modification induced by fat mass and obesity protein (FTO) is vital in MI." (PMID 39538146, 2024). "This study evaluated the effects of the FTO gene on overweight/obesity and glucose and lipid parameters in the Central China population." (PMID 39483856, 2024). "FTO, a well-known obesity gene, has also been found to influence skeletal development by regulating adipogenesis in the bone marrow." (PMID 38020896, 2023). "This review emphasizes the epigenetic influence on the FTO gene as a new approach in the treatment and management of obesity." (PMID 37200795, 2023). "In the group of girls, obesity diagnosed on the basis of BMI was more frequent among AT heterozygotes compared to TT homozygotes (4.59% vs 1.38%, χ2 = 14.14, p = 0.03) of the FTO rs9939609 gene." (PMID 38066615, 2023). "In a cohort of Northwest Mexican adults, single-nucleotide polymorphisms (SNPs) in the ABCA1 gene as well as FTO alpha-ketoglutarate-dependent dioxygenase (FTO), adrenoceptor beta 3 (ADRB3), and PPARG were associated with increased risk of obesity." (PMID 38027204, 2023). "The results on the role of FTO in depression-obesity comorbidity are inconclusive, and further research is needed to deepen knowledge of the genetic basis of this comorbidity." (PMID 37387537, 2023). "To date, many of these studies focused on an m6A eraser, FTO, due to its role in obesity and the strong link of metabolic disorders with depression." (PMID 37047192, 2023). "Obesity is highly associated with dyslipidaemia and increased risk of cardiovascular disease (CVD), with the possibility of an FTO-mediated effect on lipids." (PMID 37200795, 2023).
Obesity (continued). "FTO is one of the most commonly identified obesity-related genes (eTable 1 in Supplement 1), but prior studies have not included a wide range of racial groups or social backgrounds across the lifespan." (PMID 38064210, 2023). "Since the discovery of FTO, an additional 1,100 independent genome-wide significant loci have been identified; however, these combined explain only 6% of inter-individual obesity variation." (PMID 37664850, 2023). "The connection between obesity and cancer pathways via FTO seems to be regulated by mammalian target protein rapamycin (mTOR)." (PMID 35731272, 2023). "In this context, polymorphisms in the LEPR and FTO genes have been associated with GWG, at least in adult women, particularly in those beginning pregnancy with overweight or obesity." (PMID 36986260, 2023). "Gallocatechin is the most promising natural FTO inhibitor, as experiments showed a similarity of binding site along with a stronger affinity to orlistat, anti-obesity medicine, of more than 60%." (PMID 37200795, 2023). "Within the genes related to obesity, the FTO gene has one of the strongest links with this condition in the human population." (PMID 36983683, 2023). "Fat mass and obesity-associated protein FTO, also termed ALKBH9, is the first RNA demethylase and the first GWAS‐identified obesity gene." (PMID 36792603, 2023). "Similar molecular mechanisms play a role in the development of obesity and BCa [34, 35•], which exhibit overexpression of FTO." (PMID 36729355, 2023). "To date, the FTO gene (localized on chromosome 16) has been identified to have the greatest impact on the obesity trait in GWAS studies, and in addition, showed association with BMI value, hip circumference and body weight." (PMID 36980866, 2023). "For instance, an obesity-related SNP found in the intron of the FTO gene was found to influence the process of adipocyte browning by regulating the activity of IRX3 and IRX5, rather than directly impacting FTO itself." (PMID 36837926, 2023). "Thus, those with the FTO rs9930506 polymorphism may be at a higher risk for obesity." (PMID 37752455, 2023). "Recent studies have shown a relationship between FTO and obesity-related indices in early adolescents." (PMID 37752455, 2023). "An Important recognized gene is the FTO gene (OMIM*610966), known as “the fat mass and obesity associated gene”, which is an obesity susceptibility gene." (PMID 37375686, 2023). "The obesity-related FTO locus colocalizes for type 2 diabetes and osteoarthritis with a posterior probability of a shared causal variant of over 92%." (PMID 37433298, 2023). "It has been evidenced that single nucleotide polymorphism (SNP) rs1121980 in the FTO gene is also related to an increased risk of class II (BMI 35.0–39.9 kg/m2) and III (BMI ≥ 40.0 kg/m2) obesity in women in the Mexican population." (PMID 37569198, 2023). "Previous studies have shown that FTO and PLIN1 do not only play a role in regulating obesity; they are also significantly associated (p < 0.05) with economically important traits in pigs, sheep, and cattle." (PMID 37835645, 2023). "Active beige adipocytes with FTO risk-free genotype expressed the BATLAS marker genes at the highest level, whereas ones with the obesity-risk allele carriers expressed them at a level similar to those observed in the white or inactive beige adipocytes." (PMID 37416800, 2023). "FTO is identified as a gene of interest for obesity and has been subject to many investigations, most of which confirming that there is a notable association between FTO polymorphism and obesity traits." (PMID 37697388, 2023). "FTO rs9939609 (AA +TT) carriers and near MC4R rs17782313 (CC+TT) had a significantly higher BMI, and were associated with categorial obesity." (PMID 37664850, 2023). "Previous studies have found that LIM has low binding energy to FTO, the most relevant handle point in obesity treatment." (PMID 36678138, 2023).
Obesity (continued). "In order to estimate the link between obesity development and nesfatin-1 levels, polymorphisms of NUCB2/nesfatin-1 and the Fat mass and obesity gene (FTO) were also assessed." (PMID 36678225, 2023). "Mutated FTO (rs1421085) interacts with Iroquois-class homeodomain proteins IRX-3 and IRX-5, which are also linked to obesity in humans and animals." (PMID 36839421, 2023). "Evidence has shown the role of FTO in food intake and its primary effects on diabetes mellitus and obesity." (PMID 36717394, 2023). "The protein -protein interaction network analysis showed that PNLIP and FTO genes were identified as candidate genestargeting obesity." (PMID 37808366, 2023). "Third, in addition to the FTO gene, there are some SNPs in other genes that their relationships with obesity indices are demonstrated, but gene–gene interactions were not evaluated in this study." (PMID 38618529, 2023). "Studies from Asia have revealed that genetic predisposition to the FTO and TFAP2B genes contributed to a sex-dependent pattern of obesity-related traits and remarkable accumulation of abdominal fat." (PMID 36627697, 2023). "Previous studies have also identified numerous genetic loci and gene variants such as FTO, MC4R, ADAMTS9 and GRB14/COBLL1, which have been found to be associated with overweight/obesity and diabetes." (PMID 38089629, 2023). "FTO belongs to the AlkB protein family, and its expression is closely related to weight gain and obesity." (PMID 37701433, 2023). "Mechanistically, perturbations in the m6A methylome by FTO or other m6A regulators result in alterations in adipogenesis homeostasis, which likely promote obesity." (PMID 37404756, 2023). "A genomic region on OCU5 was associated with C16:0, SFA, PUFA, and PUFA/SFA fatty acids and included two important candidate genes directly related to lipid metabolism, binding, and obesity (FTO and RPGRIP1L)." (PMID 37835677, 2023). "Treating obesity through FTO gene regulation will have to include various complex signal pathways in which FTO takes part." (PMID 37200795, 2023). "Confirmed examples of variation in enhancer regions causing disease are few, including BCL11 in sickle cell disease and FTO in obesity." (PMID 37066790, 2023). "Based on genome-wide association analysis data, genetic variants in FTO and TFAP2B, previously known as obesity susceptibility loci, impinge independently on the risk of metabolic syndrome." (PMID 36627697, 2023). "In our study we investigated the association of polymorphisms of the FTO rs9939609 and MC4R rs1778231 genes, which have been well-documented to be related to a higher prevalence of overweight and obesity." (PMID 38066615, 2023). "There are various mechanisms proposed to explain the link between FTO and obesity, among others its role in regulating energy homeostasis, regulating the appetite and food intake directly by adipocyte or indirectly through hypothalamic expression." (PMID 37500688, 2023). "Further, with regard to therapeutic implications, FTO appears to be an interesting target due to the connection of obesity and EC." (PMID 35731272, 2023). "Numerous FTO gene variants have been reported with an amplified contributory effect on T2DM and obesity." (PMID 36980809, 2023). "The FTO rs9939609 polymorphism was independently associated with T2DM after controlling for the confounding variables including age, sex, smoking, obesity, dyslipidemia, hyperhomocysteinemia, hyperuricemia, hypertension and CAD (P < 0.01)." (PMID 38161971, 2023). "FTO is the gene most related to obesity, and the adverse cardiometabolic effects of its polymorphisms are mostly mediated by excess adipose tissue." (PMID 37240750, 2023). "The discovery of FTO has also revealed another strongly associated locus, the melanocortin 4 receptor gene (MC4R), which is associated with weight, fat mass and obesity." (PMID 36717394, 2023).
Obesity (continued). "The MC4R gene was identified as the leading contributor of monogenic obesity and the interaction of FTO and MC4R genes on certain pathways are associated with obesity-related phenotypes." (PMID 36717394, 2023). "The top two loci with the strongest association signals identified by sfkit were co-located with SLC25A48 and FTO genes, recapitulating previously reported genetic factors of obesity." (PMID 37246709, 2023). "Although studies have produced mixed results regarding the effects of obesity-risk FTO alleles on risk of AUD, alcohol consumption and AD risk do appear to moderate the effects of obesity-risk FTO alleles on BMI." (PMID 38389820, 2023). "In conclusion, only five of the 37 genetic variants previously linked to T2DM and obesity in the Saudi Arabian population [HNF4A-rs4812829, WFS1-rs1801214, DUSP9-rs5945326, ZFAND6-rs11634397, FTO-rs11642841] were associated with prediabetes susceptibility." (PMID 36980809, 2023). "In turn, obesity induces glycolysis, lipid toxicity, and pro-inflammatory phenotype by increasing FTO protein expression." (PMID 36830642, 2023). "Several of the high-confidence genes, including FTO and IRX3, are associated with obesity-related traits." (PMID 37433298, 2023). "Interestingly, active beige adipocytes carrying FTO obesity-risk genotype showed similar estimated brown adipocyte content and browning capacity as compared to white adipocytes suggesting that active beige differentiation could not overcome the browning inhibitory effect of the CC alleles." (PMID 37416800, 2023). "The FTO gene codes for a protein that plays an important part in the development of obesity and T2DM." (PMID 36983642, 2023). "Large-scale clinical research studies demonstrated that a variant of FTO enhances the expression of IRX5 and IRX3 leading to excessive adipocyte differentiation and obesity." (PMID 35428362, 2022). "Conditional endothelium-targeted knockout of FTO during continuous lipid-diet-induced obesity, vascular dysfunction, and hypertension was found to be protective against hypertensive phenotypes via a novel FTO-mediated pathway controlling myogenic tone." (PMID 35991314, 2022). "FTO (also referred to as ALKBH9) was first identified as an obesity-related gene; it exhibits dioxygenase activity that oxidizes m6A to form an N6-hydroxymethyladenosine intermediate, which is further oxidized to N6-formyladenosine." (PMID 35836571, 2022). "The BMI increasing alleles of FTO, LEPR and ADIPOQ genetic variants are common in Pakistani individuals thus increasing their risk towards obesity." (PMID 36126070, 2022). "Individuals with SNPs occurring on intron-1 of the FTO gene (rs9939609 (A/-), rs17817449 (G/-), rs3751812 and rs1421085 (C/-)) are more likely to suffer from obesity." (PMID 36278751, 2022). "Curcumin and epigallocatechin gallate prevented obesity by reducing ALKBH5 or FTO separately in an m6A-dependent manner." (PMID 36120320, 2022). "Some synthetic compounds, such as CHTB, FB23, and diacerein, occupying the αKG and/or substrate binding site have been identified as potent inhibitors of FTO, potentially regulating obesity." (PMID 35769384, 2022). "In a study group, the frequencies of carrying the riskiest genotype in relation to obesity development were the highest in the case of the FTO gene." (PMID 36142109, 2022). "Wine consumption significantly interacted with all eighteen FTO SNPs in determining FTO SNPs-related obesity, assuming a dominant model." (PMID 36235854, 2022). "An extract from Angelica sinensis and two extracts from Solanum melogena and S. aethipicum, respectively, have been shown to contribute to reducing obesity via modulation of the FTO gene." (PMID 36501129, 2022). "Putative genetic links between obesity and adiposity with PCOS are reinforced by current evidence, for instance, the influence of FTO gene variants." (PMID 35679284, 2022).